VCAM1 (vascular cell adhesion molecule 1)
Diseases named in the same sentence as VCAM1 in open-access papers (continued):
Sharing a sentence is not in itself a finding about the gene and the disease.
atherosclerosis (continued). "In this study, mice in the ApoEST2DKO group, with significant atherosclerosis development, showed increased VCAM1 and ICAM1 levels and a non-significant but decreasing trend in IL-4 and IL-5, consistent with previously reported results." (PMID 38674885, 2024). "Our in vivo data of proteomics and immunostaining showed that, compared with WT group, MerTK-/- aggravates atherosclerosis in d-flow areas through upregulation of endothelial dysfunction markers (e.g. IL-1β, NF-κB, TLR4, MAPK signaling, vWF, VCAM-1 and p22phox) and mitochondrial dysfunction." (PMID 38646649, 2024). "Therefore, IF staining was performed as well, targeting inflammatory biomarkers and endothelial markers such as VCAM-1, NF-κB, CD31, and α-SMA in samples from mice with advanced atherosclerosis." (PMID 39337364, 2024). "Additionally, Tat induces the expression of both vascular cell adhesion protein-1 (VCAM-1) and intercellular adhesion molecule-1 (ICAM-1), inferring a potential mechanism via which HIV-1 intensifies endothelial injury as well as atherosclerosis." (PMID 38411777, 2024). "Additionally, FSH contributes to the development of atherosclerosis by activating the PI3K/Akt/NF-κB pathway and boosting vascular cell adhesion molecule-1(VCAM-1 )protein expression." (PMID 39741875, 2024). "It was reported that intercellular cell adhesion molecule-1 (ICAM-1) and vascular cell adhesion molecule-1 (VCAM-1) could promote the adhesion of human monocytic THP-1 cell to HUVECs, which accelerated the development of atherosclerosis." (PMID 38239233, 2024). "This increase in VCAM-1 and ICAM-1 expression, mainly induced by proinflammatory cytokines or lipopolysaccharide (LPS), promotes leukocyte recruitment, adhesion, and transmigration into inflamed tissues and ultimately atherosclerosis." (PMID 37830604, 2023). "In the early stages of atherosclerosis there is damage of the endothelium and activation of inflammatory mediators, which include monocyte chemoattractant protein-1, IL-8 and adhesion molecules ICAM-1, VCAM-1 and E-selectin." (PMID 36672663, 2023). "Through analysis of protein functional enrichment, it was found that AR may act on IL-6, TNF-α, ICAM-1, VCAM-1, and MCP-1 and play anti-atherosclerosis and neuroprotective roles." (PMID 37361203, 2023). "After properly establishing the role of VCAM-1 in atherogenesis as a mediator of pathological monocyte infiltration, novel therapeutics blocking VCAM-1 function have emerged as an attractive strategy for treating atherosclerosis." (PMID 37595265, 2023). "In addition, VCAM-1 and ICAM-1 RNA levels are decreased, indicating that extracellular ATP induces vascular inflammation and atherosclerosis by activating P2Y2 receptor." (PMID 34981330, 2023). "Serum proteomics research results show that AR may act on IL-6, TNF-α, VCAM-1, MCP-1, and ICAM-1, and play anti-atherosclerosis and neuroprotective roles." (PMID 37361203, 2023). "Importantly, previously it was shown that miR-126-3p directly inhibits the expression of VCAM-1, and it regulates the expression of VCAM-1 in several clinical conditions, including atherosclerosis." (PMID 35596173, 2022). "Clinical studies included a more extensive list of diverse biomarkers associated with atherosclerosis development to include TNF-α, VCAM-1, ICAM-1, and several interleukins, which were not as extensively studied in observational studies." (PMID 36232062, 2022).
atherosclerosis (continued). "The activated ECs at the sites of inceptive atherosclerosis up-regulate the expression of P-selectin, intercellular adhesion molecule-1 (ICAM-1) and vascular cell adhesion molecule-1 (VCAM-1), which are critical for attracting inflammatory cells, such as monocytes, for trans-endothelial recruitment." (PMID 36304814, 2022). "VCAM-1−/− mice did not develop atherosclerosis, suggesting that VCAM-1 is required for atherogenesis." (PMID 36211578, 2022). "Also, the genes that are involved with the inflammatory responses like VCAM1, MCP1, M-CSF, IL-1β, TNF α and β, IL-6, M-CSF, MCP-1, IL-18 and CD-40L, etc. were thoroughly studied to elucidate their role in atherosclerosis." (PMID 35241081, 2022). "In contrast, hypomethylation of the LINE-1 DNA sequence may exacerbate stroke injury in relation to elevated levels of the vascular cell adhesion molecule 1 (VCAM-1), a protein that promotes vascular–immune cell interactions and mediates atherosclerosis." (PMID 36142283, 2022). "In addition, SIRT6 inhibits the adhesion of monocytes to ECs by decreasing the expression of vascular cell adhesion molecule-1 (VCAM-1) and intracellular adhesion molecule-1(ICAM-1) to relieve atherosclerosis." (PMID 36465178, 2022). "Moreover, VCAM-1 triggers monocyte migration and infiltration into the endothelium through VLA-4 in early atherosclerosis." (PMID 36467095, 2022). "This blood vessel wall damage is mainly reflected by a higher expression of both chemoattractants and binding proteins like vascular cell adhesion molecule 1 VCAM1, MCP-1, and IL-8 that allow for monocyte recruitment into the arterial wall, an important initial step in atherosclerosis onset." (PMID 36247456, 2022). "Another component that modulates TNFα-induced remodeling is the erythropoietin-producing human hepatocellular receptor (EphA), which is a receptor tyrosine kinase that mediates cell-adhesion and leukocyte homing in atherosclerosis by promoting ICAM1 and VCAM1 expression on ECs." (PMID 35600479, 2022). "There are many key molecules involved in the laminar shear stress and atherosclerosis pathways, such as endothelin 1 (EDN1), vascular cell adhesion molecule 1 (VCAM1), KLF2, intercellular adhesion molecule 1 (ICAM1), and platelet and endothelial cell adhesion molecule 1 (PECAM1)." (PMID 36364780, 2022). "Animal studies have shown that administration of sRAGE remarkably stabilizes atherosclerotic plaque, and inhibits inflammatory factors such as cyclooxygenase-2 (COX-2), VCAM-1, and monocyte chemoattractant protein-1 (MCP-1), thereby attenuating atherosclerosis progression." (PMID 35733085, 2022). "Initiation of atherosclerosis begins with aberrant endothelial cells coupled with augmented expression of surface adhesion molecules such as intercellular adhesion molecule 1 (ICAM-1), vascular cell adhesion molecule 1 (VCAM-1), and E-selectin." (PMID 36361845, 2022). "We intend to follow the localization of VCAM-1 targeted lipopolyplexes in the aortic valve and the therapeutic effect of V-LPP/shRunx2 in diabetes-induced changes in aortic heart valves in a murine model of atherosclerosis, developed previously." (PMID 35409184, 2022). "Interestingly, kaempferol treatment in atherosclerosis rabbits displayed a remarkable reduction in both the gene and protein expression of ICAM-1, VCAM-1." (PMID 34259096, 2021). "99mTc-cAbVCAM1-5 accumulated at VCAM1+ atherosclerosis lesion, while its non-targeting counterparts only showed baseline signals." (PMID 33464410, 2021). "Both VCAM-1 and S100A9-targeted TMV nano-system exhibited a distinct tropism to the plaque, indicating the tendency to apply TMV-based VNPs for imaging and the possibility to deliver drugs for the treatment of atherosclerosis." (PMID 34099630, 2021).
atherosclerosis (continued). "Based on the inhibitory effects on leukocyte adherence to the HUVECs and VCAM-1 expression, we found that eight PLE components could prevent early atherosclerosis." (PMID 34679642, 2021). "Adhesion molecules such as VCAM-1 and ICAM-1 and chemokines such as MCP-1/JE and CXCL1/KC are important modulators in monocyte recruitment, rolling, and adhesion to the vascular endothelium and play a fundamental role in the pathogenesis of atherosclerosis." (PMID 34830366, 2021). "Endothelial dysfunction is considered an early indicator of atherosclerosis and is characterized by the overexpression of adhesion molecules, including intercellular adhesion molecule-1 (ICAM-1) and vascular cell adhesion molecule-1 (VCAM-1)." (PMID 34320932, 2021). "Besides, METTL14 interacted with FOXO1 and acted directly on the promoter regions of VCAM-1 and ICAM-1, which enhanced monocyte binding to endothelial cells during atherosclerosis." (PMID 34869371, 2021). "Not only this, but the anti-VCAM-1 nanobody gave off a strong signal in the aorta of mice with varying stages of atherosclerosis, while yielding minimal nonspecific detection in control mice." (PMID 33925941, 2021). "CoQ10 could also inhibit the inflammatory proteins such as IL-6, TNF-α, ICAM-1, VCAM-1 and NLRP3, thus exerting the role inhibiting atherosclerosis." (PMID 32792941, 2020). "The adhesion molecules, vascular cell adhesion molecule-1 (VCAM-1) and intercellular adhesion molecule-1 (ICAM-1) are involved in the attraction and tethering of leukocytes to the blood vessel wall, thus have a role in both early and on-going atherosclerosis." (PMID 31923583, 2020). "Inflammatory stimuli increased the expression of the adhesion molecules E-selectin, VCAM-1, and ICAM-1 in endothelial cells, leading to increased adhesion of monocytes to the endothelium, which is one of the initial steps in the development of atherosclerosis." (PMID 32802173, 2020). "Endothelial adhesion molecules such as VCAM-1, ICAM-1, E-selectin, and P-selectin are proinflammatory proteins which play a critical role in the adhesion of leukocytes to endothelial cells during the early stages of atherosclerosis." (PMID 31840162, 2020). "Dysfunction of the endothelial cells is an important contributor to the pathobiology of atherosclerosis, and the increased secretion of adhesion molecule such as ICAM-1 and VCAM-1 in endothelial cells facilitates the macrophage adhesion to endothelial cells (Gimbrone and García-Cardeña, 2016)." (PMID 33442380, 2020). "Further, VCAM-1, platelet glycoprotein (GP) Ibα, junctional adhesion molecule A (JAM-A), GP VI, lectin-type oxidized low-density lipoprotein receptor 1 (LOX-1), and von Willebrand factor (VWF) have been used for atherosclerosis imaging." (PMID 32998422, 2020). "Interestingly, hCB-ECs intrinsically have a lower production of the VCAM-1 and ICAM-1 which correlates to reduced recruitment of leucocytes/macrophages and thus a reduced probability of graft intimal hyperplasia and atherosclerosis in vivo." (PMID 30720769, 2019). "Further studies also indicated that LOX-1 upregulation in endothelial cells promotes cell adhesion molecules (VCAM-1, etc.), monocyte chemoattractant protein (MCP-1), and inflammation related proteins expression, which advanced the development of atherosclerosis." (PMID 30402125, 2018). "Vascular cell adhesion molecule-1 (VCAM-1) is believed to play a role in the development of atherosclerosis, so the detection of VCAM-1 could be used to diagnose atherosclerosis even before clinical symptoms arise." (PMID 29751641, 2018). "Furthermore, miR-126 counteract atherosclerosis inducing CXCL12 production and influence inflammation by controling endothelial expression of VCAM1." (PMID 29937989, 2018).
atherosclerosis (continued). "Studies in ApoE−/− mice indicate that supplementation with curcumin leads to less macrophage infiltration in atherosclerosis plaque, reduced aortic NF-κB activation, reduced levels of IL-1B and TNF-α, and reduced expression of the adhesion molecules ICAM-1 and VCAM-1." (PMID 30518065, 2018). "In addition to VCAM1, MCP-1 is known to be one of the major chemokines inducing the development of atherosclerosis." (PMID 30643517, 2018). "The expression of ICAM-1 and VCAM-1 in cardiac muscle did not change after the onset of atherosclerosis." (PMID 30505360, 2018). "The levels of the atherosclerosis-related factors, osteopontin and vascular cell adhesion molecule-1, which increased in activated endothelial cells lacking glycocalyx, were normalized by sulodexide." (PMID 29207649, 2017). "The increase of vascular adhesion, observed by us in rabbits fed with Met excess, is consequent to the expression and production of adhesion molecules by endothelial cells, such as VCAM-1, E-selectin, and ICAM-1, the latter indicating the advanced stage of atherosclerosis." (PMID 28133545, 2017). "In this study, we investigated the effects of DISGT on atherosclerosis-related markers, including intercellular adhesion molecule-1 (ICAM-1), vascular cell adhesion molecule-1 (VCAM-1), and E-selectin, in high-fat diet (HFD)-induced apolipoprotein E-deficient (ApoE−/−) mice." (PMID 27608856, 2016). "The expression of VCAM-1, ICAM-1, and p-selectin plays a role in triggering the inflammatory process and has been indicated as a possible link of a low-grade chronic inflammatory process to atherosclerosis and various endocrine disorders." (PMID 27478508, 2016). "In the present study, despite the evidence of local inflammation and increased atherosclerosis in regions of High-VCAM-1, neither phospho-rylated- nor total-eNOS is reduced compared to less diseased regions." (PMID 26702331, 2015). "Therefore, VCAM-1 seems to have a more crucial role than ICAM-1 in the two major mechanisms leading to increased LVMI, i.e. atherosclerosis and hypertension." (PMID 26398099, 2015). "In apoE knockout rats, occlusal disharmony may induce VCAM1, ICAM1 and TLR4 expression and accelerate the initiation of atherosclerosis." (PMID 25189624, 2014). "We found that the fine particles obviously induced both mRNA and protein expression of VCAM-1 and ICAM-1 in HUVECs, which may contribute to PM-accelerated atherosclerosis." (PMID 24987196, 2014). "In conclusion, in the apoE knockout rats, occlusal disharmony may induce VCAM1, ICAM1 and TLR4 expression and accelerate the initiation of atherosclerosis." (PMID 25189624, 2014). "Many mRNA expressions of adherent and atherosclerosis-related factors were increased but not statistically significant except VCAM-1 and transforming growth factor-beta 1 (TGF-β1) in the adenine rats." (PMID 24829798, 2014). "However, the most important adhesion molecules involved in atherosclerosis appear to be intercellular cell adhesion molecule-1 (ICAM-1), endothelial cell selectin (E-selectin), and vascular cell adhesion molecule-1 (VCAM-1)." (PMID 24129228, 2013). "A combination of markers such as VCAM-1 and cadherin-5 and LUM and ECM-1 in synovial fluid of RA patients could potentially reflect progression of RA with a corresponding increase in atherosclerosis." (PMID 24010407, 2013). "Furthermore, remnant lipoproteins directly promote the initial stages of atherosclerosis through regulating the expression of ICAM-1 and VCAM-1, which are required for attachment of monocytes to the endothelial wall." (PMID 23621905, 2013). "Thus, VCAM-1 expression increases vascular endothelium permeability and leukocyte TEM, contributes to vascular damage and ETD, and induces the generation of atherosclerosis." (PMID 24499567, 2013). "We also expect that human anti-VCAM-1 mAb may have therapeutic effects on conditions related to VCAM-1 overexpression, such as atherosclerosis." (PMID 23855490, 2013).
atherosclerosis (continued). "The inflammatory process of atherosclerosis begins when excess LDL particles accumulate in the arterial intima and undergo oxidative modification, resulting in recruitment of circulating monocytes via factors including MCP-1 and VCAM-1." (PMID 23983803, 2013). "IgG antibodies against herpesviruses, carotid intima-media thickness (cIMT), endothelial function through flow-mediated dilatation (FMD) of the brachial artery, and blood atherosclerosis biomarkers (hsCRP, TNF-α, IL-6, MCP-1, MDA, sCD14, sCD163, VCAM-1, ICAM-1, D-dimer, and PAI-1) were measured." (PMID 23717597, 2013). "Levels of serum IL-1β and TNF-a dropped, mRNA and protein expression of E-sel, VCAM-1, ICAM-1 and MCP-1 in the aorta of rabbits were respectively down-regulated by the treatment of kaempferol, indicating that kaempferol can prevent atherosclerosis by alleviating vascular inflammation." (PMID 23895132, 2013). "The decreases of VCAM-1 and ICAM-1 of the present study suggested that moderate consumption of TFL and TCL may have a protective effect on the initial phases of the atherosclerosis process." (PMID 22919307, 2012). "In addition, we will evaluate the effects of probucol and cilostazol combination therapy on the atherosclerosis biomarkers, oxidized LDL, VCAM-1, and vWF." (PMID 21226953, 2011). "VCAM-1 is not constitutively expressed but is upregulated at atherosclerosis-prone sites even before macroscopic disease is apparent, with persistent expression in more advanced atherosclerotic lesions." (PMID 19883911, 2010). "Our data show that ApoE−/− PGC-1α−/− and ApoE−/− PGC-1α+/+ mice do not differ with regard to atherosclerosis, features of plaque vulnerability, expression of VCAM-1, and T cells number." (PMID 21042583, 2010). "Additionally, MMP-2 interacts with the protease-activated receptor 1 on endothelial cells, which in turn increases the expression of the vascular cell adhesion molecule 1 (VCAM-1) and increases monocyte subintimal layer infiltration, which ultimately results in atherosclerosis." (PMID 40724524, 2025). "In particular, antibodies against vascular cell adhesion molecule (VCAM)-1 have attracted significant research attention for their capacity to selectively bind to inflamed regions of the vascular endothelium during atherosclerosis while avoiding adjacent, non-inflamed tissues." (PMID 41367412, 2025). "The data presented in our study, however, shows that an anti-VCAM-1 mAb specific to domain 2 and not domain 1– 3H4 mAb –was able to reduce monocyte adhesion and transmigration using in vitro models of early atherosclerosis." (PMID 41367412, 2025). "This leads to decreased expression of vascular cell adhesion molecule-1 (VCAM-1) and intercellular adhesion molecule-1 (ICAM-1) in endothelial cells, reduced adhesion of monocytes to endothelial cells, and ultimately inhibiting the initiation and progression of atherosclerosis." (PMID 41011612, 2025). "It has been established that the early stages of atherosclerosis involve the attachment of leukocytes to the endothelial cells lining the arteries, facilitated by adhesion molecules like intracellular adhesion molecule-1 (ICAM-1) and vascular cell adhesion molecule-1 (VCAM-1)." (PMID 39338154, 2024). "In terms of immune/inflammation, we found that 13 absorbed constituents including salvianolic acids A, B, and C; rosaminic acid; tanshinone IIA; and cryptotanshinone could inhibit the adhesion and migration of monocytes in atherosclerosis by regulating adhesion molecules such as ICAM1 and VCAM1." (PMID 38794213, 2024).